SST (somatostatin)
Diseases named in the same sentence as SST in open-access papers (continued):
Sharing a sentence is not in itself a finding about the gene and the disease.
colon carcinoma (14 papers, 2005 to 2023). "It is believed that loss of SST synthesis in mucosa of patients with colon cancer might contribute to enhanced cell proliferation and promoter hypermethylation, possibly responsible for epigenetically reduced expression of SST in CRC." (PMID 38203605, 2023). "SST and SSTR1-5 are well expressed in HT29 cells derived from low grade differentiated tumor whereas cell obtained from high grade and undifferentiated colon cancer namely SW480 are devoid of SST and SSTR5." (PMID 38203605, 2023). "Studies have shown that SST is not only a therapeutic alternative in colon cancer treatment but has also been used as a tool in detection of colon cancer with high expression of SSTR subtypes." (PMID 38203605, 2023). "In agreement with the results observed in CRC samples, SST promotor methylation levels were also significantly increased when focused specifically on primary colon cancer samples compared to normal colonic mucosae, i.e. 88% versus 47%, respectively." (PMID 33085037, 2021). "5-AZA-dC has been shown to induce demethylation of the SST gene and/or concomitantly increased SST protein expression levels in cell lines derived from colon cancer, renal cell carcinoma and esophageal cancer." (PMID 33085037, 2021). "The involvement of the epigenetic machinery in the regulation of SST has also been demonstrated in several studies focusing on colon cancer and CRC." (PMID 33085037, 2021). "SPI and WPH induction of somatostatin, a known anti-proliferative agent for colon cancer cells, would inhibit tumorigenesis." (PMID 15644144, 2005). "Furthermore, SST has been shown to control the feedback system between colon neuroendocrine cells and colon cancer stem cells through SSTR1 to regulate stem cell quiescence and proliferation." (PMID 38203605, 2023). "Furthermore, cell death and suppression of cell proliferation upon treatment of colon cancer cells with OCT support the role of SST in regulation of epithelial cell kinetics." (PMID 38203605, 2023). "Keeping high stroma in mind, inhibition of gastrointestinal secretion with SST analogues is an indication that SST might be an effective therapeutic alternative in colon cancer treatment." (PMID 38203605, 2023). "Indeed, our study shows that SSTR1+ and GLP-2R+ cells produce their own corresponding ligands in normal crypts as well as in colon carcinomas (SST and GLP-2, respectively)." (PMID 33112876, 2020). "Our observation that in colon cancer cells octreotide significantly enhanced cell death and attenuated cell proliferation suggests that SST may act as a regulator of epithelial cell kinetics." (PMID 25723531, 2015). "Finally, NCI-H716 cells have features of endocrine differentiation, ccurring in less than 1% of colon cancer, including expression of receptors for serotonin, gastrin and somatostatin, and expression of cytoplasmic core granules." (PMID 24968263, 2014). "SST via activation of SSTR3 and -5 decreases COX2 expression and resulted in inhibition of cell proliferation of colon cancer cells through inhibition of MAPK pathways via PTP activation." (PMID 38203605, 2023). "In addition to normal and human tumor tissues variable expression of SST and SSTR subtypes has been described in in vitro in cultured colon cancer cells." (PMID 38203605, 2023).
gastritis (14 papers, 2011 to 2023). Inflammation of the stomach. "Th1 cytokines like IL-6 promote chronic atrophic gastritis and predisposition to tumorigenesis through inhibition of gastrin and somatostatin." (PMID 32231118, 2020). "In particular, gastritis caused by H. pylori causes a decrease in somatostatin levels." (PMID 34698140, 2021). "Finally, antral predominant H. pylori-associated gastritis has also been reported to locally decrease the expression of the gastrin-inhibiting peptide somatostatin." (PMID 34867785, 2021). "Gastritis caused by H. pylori also reduces somatostatin levels." (PMID 34698140, 2021). "Gastritis induced by HP infection could affect the secretion of gastric-related hormones such as leptin, ghrelin, gastrin and somatostatin, which might influence a predisposition to DM." (PMID 30779804, 2019). "And this type of gastritis usually resulted in increasing gastric acid secretion, and even duodenal ulcers because the parietal cells were hyper-stimulated by the gastrin and somatostatin-secreting cells due to antral inflammation." (PMID 38129568, 2023). "Normal gastric mucosal development requires gastrin, somatostatin, and H+K+ATPase; however, all three are greatly diminished in mice with gastritis and tumorigenesis." (PMID 32231118, 2020). "Subsequently, it was discovered that immunoreactive somatostatin, D cells, and somatostatin message were all decreased in patients with gastritis." (PMID 23606834, 2013). "The other one; H. pylori-induced gastritis can potentially affect the secretion of gastric hormones, including leptin, ghrelin, gastrin, and somatostatin, which could affect insulin sensitivity and glucose homeostasis." (PMID 27148410, 2016). "It has been reported that Interferon-γ suppresses somatostatin expression resulting in inhibition of IL4 production, which otherwise is stimulated by somatostatin to reverse H. pylori-induced gastritis." (PMID 21445336, 2011).
pituitary adenomas (14 papers, 2010 to 2025). "In an in vitro experiment, proopiomelanocortin-derived peptide secretion from a pituitary adenoma causing NS was reduced by somatostatin-14 and somatostatin-28." (PMID 37332454, 2023). "It has been shown that SST-mediated growth inhibition of human pituitary adenoma and GH3 cells is associated with the down-regulation of pERK and upregulation of p27." (PMID 25009500, 2014). "This article reviews briefly the basic biological characteristics of SST and selected studies focusing on their immunohistochemical evaluation in pituitary adenomas, and their quantification as predictors of response to treatment with SRL." (PMID 39473262, 2025). "As determined using the rabbit mAb UMB-1, SST2 also represents the most prominent SST subtype in tumor tissues, with only few exceptions, such as pituitary adenomas." (PMID 30232095, 2018). "Once again, these findings invite further exploration of the potential value of SST-DA chimeric compounds as therapeutic approaches for patients with pituitary adenomas." (PMID 28181484, 2017). "Pasireotide also showed a better clinical outcome in cats with SST‐expressing pituitary adenomas." (PMID 39011594, 2024). "SST has an inhibitory action on GH secretion; therefore, it has been hypothesized that in studies conducted on males with pituitary adenomas, SSA played a role in the impairment of male fertility." (PMID 35887747, 2022). "Furthermore, SST expression generally decreases with a higher tumor grade as demonstrated in different NETs including pituitary adenomas, GEP-NETs, pheochromocytomas and paragangliomas, neuroblastoma, Merkel cell carcinoma and medullary thyroid carcinoma." (PMID 31336364, 2019). "From these results, we can estimate that somatostatin and dopamine analogues' ability to affect these pituitary adenoma cells could be very limited." (PMID 27340409, 2016). "Besides the inhibitor effects on GH secretion, somatostatin analogues display an antiproliferative effect in primary cultures from human GH-producing pituitary adenomas (for reviews, see57)." (PMID 26549306, 2015). "Interestingly, the direct antiproliferative effects of SST analogs in pituitary adenoma cells are dissociated from the antisecretory effects, as shown by the differential responses to selective analogs." (PMID 23476673, 2013). "Moreover, SST agonists are clinically effective as antitumor agents for pituitary adenomas and gastro-pancreatic neuroendocrine tumors." (PMID 23476673, 2013). "Medical therapy with DA, and possibly also somatostatin, may be effective in controlling hormone-secreting pituitary adenomas." (PMID 20847907, 2010). "Chimeric somatostatin/dopamine compounds such as BIM-23A760, an sst2/sst5/D2 receptors-agonist, have emerged as promising new approaches to treat pituitary adenomas." (PMID 28181484, 2017). "Pituitary adenomas and gastroenteropancreatic (GEP) NETs represent the major tumor targets for SST analogs presently used in clinical practice." (PMID 23476673, 2013). "SSTR2A, SSTR3, and SSTR5 are highly expressed in corticotroph pituitary adenomas and differ from nonadenomatous tissue, providing a promising target for medical treatment with somatostatin analogs." (PMID 30627156, 2018). "In this context, we hypothesize that targeting the SST with pasireotide, a ligand with high affinity for SST5, might result in better sensitivity for occult EAS, knowing that the expression of SST5 mRNA in pituitary adenoma corticotrophs is five- to ten-fold higher than that of SST2 mRNA." (PMID 25861450, 2015). "Inhibition of pituitary adenoma cell proliferation in response to native SST or lanreotide is mediated by increased PTP activity, as observed in primary cell cultures of human GH-secreting or nonfunctioning pituitary adenomas." (PMID 23476673, 2013).
bipolar disorder (13 papers, 2008 to 2026). A disorder of the brain that causes unusual shifts in mood, energy, activity levels and the ability to carry out day-to-day tasks. "Changes in somatostatin are also identified in bipolar disorder, which is clinically characterized by fluctuating mood." (PMID 24058344, 2013). "In addition, patients with bipolar disorder show elevated CSF somatostatin during manic states." (PMID 24058344, 2013). "Only with the network approach, HCN2’s gene scores in Exc_L2-3 were positively correlated with bipolar disorder PRS, and its expression in Exc_L2-3 showed positive correlations with other excitatory neuron populations but negative correlations with VIP and SST interneurons (In_VIP and In_SST)." (PMID 40053590, 2025).
Parkinson disease (13 papers, 2013 to 2025). A progressive degenerative disorder of the central nervous system characterized by loss of dopamine producing neurons in the substantia nigra and the presence of Lewy bodies in the substantia nigra and locus coeruleus. "Overall, our study reveals the cortical SST interneurons as a promising therapeutic target for Parkinson’s disease." (PMID 32404907, 2020). "Decreased CSF somatostatin, decreased somatostatin immuno-reactivity, and binding sites are also observed in the temporal cortex and frontal cortex of patients with Parkinson’s disease." (PMID 24058344, 2013). "Alterations in pre-BötC NK1R and SST neurons has been previously reported in SIDS and neurodegenerative diseases such as multiple system atrophy and Parkinson’s disease associated with disordered breathing." (PMID 29608654, 2018). "Notably, reduced CSF somatostatin in Parkinson’s disease appears to be irreversibly present at the onset of symptoms." (PMID 24058344, 2013). "Ample evidence suggests that an imbalance in dopaminergic tone impacts the expression levels of neuropeptides like somatostatin (SST) and neuropeptide Y (NPY), as seen in patients with Parkinson’s disease and HD as well as in rodent models." (PMID 39468205, 2024).
colorectal cancer (11 papers, 2008 to 2023). A primary or metastatic malignant neoplasm that affects the colon or rectum. "Hypermethylation of the SST promoter region has also been associated with uncontrolled cell proliferation in colorectal cancer." (PMID 38203605, 2023). "Differential expression and PPI network analysis also revealed SST that was one of the genes with the highest AUC value in terms of diagnostic efficiency in colorectal cancer." (PMID 35486660, 2022). "Therefore, reduced somatostatin levels, which we found in a pilot study might have relevance in gastrointestinal tumorigenesis including colorectal cancer which is one of the leading causes of cancer-related death." (PMID 25723531, 2015). "SST and its analogs have been shown to inhibit tumour growth in colorectal cancer cell lines and models positive to SSTR2 both in vivo and in vitro." (PMID 38203605, 2023). "The VIP and SST genes reported in another study that applied network-based algorithms to find prognostic markers in colorectal cancer." (PMID 35486660, 2022). "One of these targets was SST with a down-regulated expression in colorectal cancer samples, this result was also observed in our study." (PMID 35486660, 2022). "Quantitative RT-PCR results have shown that the following 3 core genes were significantly different between colorectal cancer tissues and normal colorectal tissues: SST, CXCL8, and MS4A12." (PMID 32462020, 2020). "In agreement with our results, there are reports on SST hypermethylation in gastrointestinal tract malignancies including esophageal, stomach, and colorectal cancer." (PMID 32243066, 2020). "Colonic samples were collected from healthy children (n1 = 6), healthy adults (n2 = 41) and colorectal cancer patients (CRCs) (n3 = 34) for SST mRNA expression analysis, using HGU133 Plus2.0 microarrays." (PMID 25723531, 2015). "As we are aware, this is the first study to compare somatostatin expression in colorectal epithelium of healthy children and adults to that found in colorectal cancer samples both at mRNA and protein levels." (PMID 25723531, 2015). "In few studies on the role of SST in colorectal cancer, we speculate that SST has a similar role in colorectal cancer." (PMID 32462020, 2020). "Hypothesis: SSTR1 cells maintain SCs in a quiescent state, and aberrant SST signaling contributes to SC overpopulation in colorectal cancer (CRC)." (PMID 27927191, 2016). "However, in colorectal cancer wherein increased cell growth is dysregulated, SST methylation was significantly higher (30.2%±11.6%) (p<0.05)." (PMID 25723531, 2015). "Similarly to these markers, significantly decreased SST production may also contribute to colorectal cancer formation." (PMID 25723531, 2015). "Analysis using qRT-PCR has shown that SST, CXCL8, and MS4A12 were significant differentially expressed between colorectal cancer tissues and normal colorectal tissues (P < 0.05)." (PMID 32462020, 2020). "So far in clinical studies, the effect of SST and its analogs on preventing tumour progression in patients with colorectal cancers are not any different than a placebo." (PMID 38203605, 2023). "Moreover, our data is consistent with previous reports showing that SST, the other main ligand of SSTR-subtypes, also plays an important autocrine/paracrine role in several cellular models including colorectal cancer cells." (PMID 36361790, 2022). "In addition, 3 core genes (SST, CXCL8, and MS4A12) were found to be significantly differentially expressed between colorectal cancer tissue and normal colorectal tissue using qRT-PCR." (PMID 32462020, 2020). "In this study we demonstrated both at mRNA and protein levels that somatostatin expression does not differ significantly in elderly healthy colonic epithelium compared to juvenile samples, however, it is nearly absent in colorectal cancer." (PMID 25723531, 2015).
colorectal cancer (continued). "mRNA expression of SST did not alter during normal aging as compared healthy juvenile (Ch) and adult (N) samples, however, gene expression significantly decreased in colorectal cancer (CRC) (p<0.05) compared to normal adult (N) samples." (PMID 25723531, 2015). "Immunohistochemical analysis confirmed the nearly absent somatostatin production in colorectal carcinoma samples as compared to young and adult healthy colonic mucosa on protein level (p<0.05)." (PMID 25723531, 2015).
glioma (11 papers, 2011 to 2024). A benign or malignant brain and spinal cord tumor that arises from glial cells (astrocytes, oligodendrocytes, ependymal cells). "In this regard, some reports have suggested an association between clinical outcome and the expression of SST in glioma, thyroid cancer, and lung cancer." (PMID 32335823, 2020). "Tat-NTS peptide blocks the proliferation, migration, and invasion of glioma cells, PACAP exerts an antiproliferative effect against glioma cells and reduces invasion, and somatostatin suppresses the migration of glioma cells." (PMID 39063232, 2024). "SST inhibits the migration in glioma cells by involving PI3-K and Rac activity, supporting the role of SST in regulation of invasion and metastases of glioma." (PMID 38203605, 2023). "Cell line-specific responses were also reported for gliomas, only demonstrating SST upregulation upon 5-AZA-dC treatment in cell lines characterized by promotor hypermethylation." (PMID 33085037, 2021). "SHP2 is expressed in several SST-responsive tumors including gliomas and neuroblastomas as well as in thyroid cells." (PMID 23476673, 2013). "Eight promoter-hypermethylated genes (ANKDD1A, GAD1, HIST1H3E, PCDHA8, PCDHA13, PHOX2B, SIX3, and SST) were confirmed in primary glioma and cell lines." (PMID 21962230, 2011). "In addition, antiproliferative effect of SST in glioma cells has also been reported through increasing DEP-1/PTP activity and inhibition of ERK1/2 activity." (PMID 38203605, 2023). "SST hypermethylation has also been reported for human tissue derived from cervical cancer and anal cancer, and both in cell lines and human tissue derived from esophageal carcinomas, gliomas as well as HNSCC." (PMID 33085037, 2021). "The results of this study support previous attempts of somatostatin targeting in glioma." (PMID 32335823, 2020). "Importantly, in glioma cell lines and primary cultures from human glioblastomas, the cytostatic activity of SST was dependent on the expression and activation of PTPη." (PMID 23476673, 2013). "In addition, we found that the percentages of promoter methylation in the ANKDD1A and PHOX2B, but not the GAD1, HIST1H3E, PCDHA8, PCDHA13, SIX3 and SST, were associated negatively with the differentiation degrees of human gliomas." (PMID 21962230, 2011). "The GAD1, HIST1H3E, PCDHA8, PCDHA13, SIX3 and SST may regulate the progression of glioma." (PMID 21962230, 2011). "The glioma cell lines U251 and SF767 are characterized by 51.6% and 77.1% methylation of the SST promotor, respectively." (PMID 33085037, 2021). "Using C6 rat glioma cells, an experimental model that in vivo closely reflects invasion and neovascularization of human GBM growth, the efficacy of SST analogs was assayed on tumor growth in nude mice." (PMID 23476673, 2013). "The methylation levels of seven gene promoters (ANKDD1A, GAD1, SIX3, SST, PHOX2B, PCDHA8, and HIST1H3E) in glioma patients and cell lines were significantly higher than those in non-tumor controls (p < 0.01)." (PMID 21962230, 2011). "Other SHH-1A associated genes were the neuroendocrine-specific tumor genes SST and SCG2; ARPP21, encoding an RNA-binding protein found in glioma, and SOX6, a tumor marker expressed by not fully differentiated neuronal and glial cells." (PMID 35501487, 2022). "SSTR2 could mediate the cytostatic effects of somatostatin by activating phosphotyrosine phosphatase PTPeta and inhibiting ERK1/2 activity in C6 glioma cells." (PMID 34961815, 2021).